SNORA63B (small nucleolar RNA, H/ACA box 63B)
Gene: Small nucleolar RNA gene on chromosome 3 (186,786,323 to 186,786,445, forward strand). Ensembl gene ENSG00000200418.
Gene Ontology:
Biological process: RNA processing
Cellular component: nucleolus
Homologues: Orthologues: macaque SNORA63 (94% identical), chimpanzee SNORA63 (92% identical), guinea pig SNORA63 (86% identical), mouse Gm24201 (85% identical), pig SNORA63 (85% identical), rat LOC120095727 (84% identical), tropical clawed frog SNORA63 (71% identical), tropical clawed frog SNORA63 (70% identical), zebrafish SNORA63 (63% identical). Paralogues in human: SNORA63 (83% identical), SNORA63 (77% identical), SNORA63 (75% identical), SNORA63 (73% identical), SNORA63D (71% identical), SNORA63 (70% identical), SNORA63C (67% identical), SNORA63E (67% identical), SNORA63 (33% identical).